TNF (tumor necrosis factor)
Diseases named in the same sentence as TNF in open-access papers (continued):
Sharing a sentence is not in itself a finding about the gene and the disease.
histiocytic lymphoma (7 papers, 2013 to 2023). "Inhibition of TNF-α mediated apoptosis by measuring caspase activation in the U937 cell-line, a human histiocytic lymphoma, which exhibits properties typical of macrophages was also used (n=3)." (PMID 33936049, 2021). "It has also been reported that apoptotic stimulators, such as staurosporine, TNF-α, and ETO increased cATP production levels in HeLa, rat pheochromocytoma (PC12), and human histiocytic lymphoma (U937) cells." (PMID 26522181, 2015). "We first used the human histiocytic lymphoma cell line U-937 as a differentiation model since U-937 cells are induced to monocytic/macrophage-like differentiation by phorbol esters, ATRA, 1-α-25-dihyroxycholecalciferol (vitamin D3), gamma interferon, or tumor necrosis factor." (PMID 24466208, 2014).
hyperparathyroidism (7 papers, 2010 to 2023). Hyperfunction of the parathyroid glands resulting in the overproduction of parathyroid hormone. "PPR-dependent stimulation of TNF production by T cells and the resulting TNF regulation of CD40 signaling in SCs are potential new therapeutic targets for the bone loss of hyperparathyroidism." (PMID 20808842, 2010). "Bone loss is explained by the overproduction of cytokines IL-1 alpha, IL-1 beta and TNF-alpha and will be further accelerated by hyperparathyroidism secondary to malabsorption of calcium and vitamin D. these mechanisms will contribute to increased bone resorption and activate bone loss." (PMID 25667705, 2014). "Bone loss is explained by the overproduction of cytokines IL-1 alpha, IL-1 beta and TNF-alpha which is further accelerated by hyperparathyroidism connected with malabsorption of calcium and vitamin D. Interaction of both these mechanisms increases bone resorption and activates bone loss." (PMID 22593794, 2012). "In this context, patients with hyperparathyroidism will, theoretically, have higher levels of IL-6, CRP, or tumor necrosis factor-α (TNF-α)." (PMID 24782595, 2014).
hypersensitivity reaction (7 papers, 2013 to 2023). "A hypersensitivity reaction was the only adverse event reported by > 5% of patients during vedolizumab treatment (4 patients; 5.8%) and a cutaneous reaction was the only adverse event reported by > 5% of patients during anti-TNFα treatment (6 patients; 5.7%)." (PMID 32640990, 2020). "The persistence of a pathogenic agent within macrophages can lead to typical granuloma formation in the context of a type IV hypersensitivity reaction in whose formation T lymphocytes, cytokines such as TNF, IFN-γ, as well as eosinophils and IgE are directly involved." (PMID 23637975, 2013).
Klebsiella pneumonia (7 papers, 2005 to 2021). An pneumonia caused by infection with Klebsiella. "TNF can enhance phagocytosis of phagocytes, and over-expression of TNF heightens the clearance of bacteria in Klebsiella pneumoniae pneumonia." (PMID 30189656, 2018). "In contrast to the observation in our experiments in AM-depleted LPS-lungs, an increase of TNF-α in the AM-depleted Klebsiella pneumonia lungs was observed 2 days after the onset of the injury." (PMID 15972102, 2005). "Analysis of cytokine responses of respiratory leukocytes after stimulation with Klebsiella pneumonia indicated reduced IFN-γ and TNF-α expression and increased IL-10 and IL-12p70 production after 7 day low dose skin TLR7 triggering." (PMID 22927956, 2012).
Left ventricular diastolic dysfunction (7 papers, 2009 to 2023). Abnormal function of the left ventricule during left ventricular relaxation and filling. "Studies had confirmed the relationship between CRP, TNF, and CSAP, which indicated TNF-α had an association with left ventricular diastolic dysfunction while CRP was related to the reoccurrence of CSAP." (PMID 33110434, 2020). "Regardless of sex, hypertensive patients with the second stage of the left ventricular diastolic dysfunction have significantly higher (compared to the first stage) systemic blood concentrations of C-reactive protein, tumor necrosis factor alpha, and interleukin-6." (PMID 35997392, 2022). "In particular increased plasma levels TNF-α and IL-6 seem to be correlated with impaired LVDD and more advanced left ventricular diastolic dysfunction." (PMID 19909503, 2009).
manic episodes (7 papers, 2017 to 2024). "Research shows that peripheral blood TNF-α levels are significantly greater in patients with a normal mood and in healthy individuals during manic episodes than in healthy individuals." (PMID 38505796, 2024). "Other studies found that treatment responders who had suffered a manic episode experienced a significant reduction in TNF-α levels." (PMID 38720780, 2024). "Compared to healthy people, BD patients with acute manic episodes had significantly increased serum IL-6, TNF-α, IL-1RA, and sIL-2R." (PMID 37662097, 2023). "For instance, the level of TNF-α in BD patients increased during both depressive and manic episodes." (PMID 29065864, 2017). "Increased levels of IL-6 and TNF-α have also been noted during manic episodes." (PMID 38672750, 2024). "In patients experiencing a manic episode, pro‐inflammatory cytokines (e.g., TNF‐α, IL‐1, IL‐6), soluble receptors of IL‐2, soluble TNF‐α receptor type 1 (sIL‐2R and sTNFR1, respectively), and C reactive protein (CRP) are generally increased when compared to a control population." (PMID 34590391, 2022). "Also, the serum TNF-α was elevated in patients with depressive or manic episodes but not in euthymia, while IL-6 remained elevated regardless of the disease state." (PMID 37662097, 2023).
mucocutaneous leishmaniasis (7 papers, 2014 to 2024). The most common form of leishmaniasis that is transmitted through the bite of female phlebotomine sand flies or after exposure to leishmania parasites. "The highest TNF-α upregulation was found in L. guyanensis infected MΦ, which could be related to infection pathogenesis since this parasite can cause mucocutaneous leishmaniasis." (PMID 37190011, 2023). "Considering the plasma levels of TNF-α in two HIV-uninfected patients with active mucocutaneous leishmaniasis evaluated at our laboratory (22 pg/mL and 13 pg/mL), the levels observed in this patient during IRIS were similar." (PMID 25645330, 2015).
mycobacterial infections (7 papers, 2014 to 2025). "Multiple studies in the past years have established the specific correlation between anti-tumor necrosis factor alpha (anti-TNF-a) agents and mycobacterial infections." (PMID 37512971, 2023). "The connection between TNF production and apoptosis of macrophages in response to mycobacterial infection along with reduction in the bacterial load has also been demonstrated." (PMID 34987503, 2021). "Notably, the proapoptotic role of the TNF-α–caspase-8 axis is not well narrated in piscine mycobacteriosis." (PMID 34987503, 2021).
myocardial disease (7 papers, 2015 to 2024). "Beyond traditional causes of myocardial disease, adverse remodeling is mediated by systemic metabolic dysregulation including circulating metabolic substrates [e.g., free fatty acids (FFAs)] and inflammatory cytokines [e.g., tumor necrosis factor-alpha (TNF-α) and IL-6]." (PMID 34671656, 2021). "Although no universally accepted definition or diagnostic criteria for septic cardiomyopathy exist, it is a reversible myocardial disorder driven by inflammatory mediators such as endotoxin, tumor necrosis factor-alpha (TNF-α), and interleukin-1-beta (IL-1β)." (PMID 39479085, 2024). "TNF-α has also been discussed as a marker for myocardial disease and has been shown to be produced in cardiac myocytes and endothelium." (PMID 37554366, 2023).
nasopharyngitis (7 papers, 2019 to 2025). An inflammatory process that affects the nasopharynx. "Nasopharyngitis (ROR = 3.15, 95% CI [2.89–3.42], n = 629) was the most frequently reported PT, with risk signals detected across all five TNF-α inhibitors." (PMID 41329755, 2025). "In chronic nasopharyngitis, inflammatory cytokines such as tumor necrosis factor alpha (TNF-α), interleukin 6 (IL-6), and IL-1β are persistently elevated in NALT, contributing to systemic fatigue, low-grade fever, and immune hypersensitivity." (PMID 41024755, 2025). "However, tumor necrosis factor alpha inhibitors significantly increased the incidence rate of common adverse events, including nasopharyngitis, headache, and injection-site reactions." (PMID 36865909, 2023).
neuromyelitis optica (7 papers, 2009 to 2025). A rare inflammatory disease of the central nervous system characterized mainly by attacks of uni- or bilateral optic neuritis (ON) and acute myelitis. "Indeed, BTK inhibition dampens microgliosis in LPS-induced neuroinflammation and chronic white matter ischemia and enhances microglial phagocytosis while reducing microglial TNF-α in vivo in the animal model of neuromyelitis optica." (PMID 40607415, 2025).
Onset (7 papers, 2014 to 2025). The age group in which disease manifestations appear. "It has also been shown that increased levels of cytokines such as IL-2, IL-6, IL-8, TNF-α in subjects with new-onset AF, can stimulate mesothelial cells to produce CA125." (PMID 31058877, 2019).
oral cavity cancer (7 papers, 2013 to 2025). A primary or metastatic malignant neoplasm involving the oral cavity. "Subsequent studies have identified higher concentrations of TNF and interleukins (IL-6 and IL-8) in patients with oral cavity cancer." (PMID 40733296, 2025). "Nakano and collaborators (1999) identified elevated concentrations of pro-inflammatory cytokines TNF and IL-6 in tumor tissues of oral cavity cancer patients." (PMID 40733296, 2025). "The pro-inflammatory cytokine TNF was present in high concentrations in two oral cavity cancer cell models (HSC3 and SCC9), and this cytokine mediated nociception and inflammation induction in this type of cancer." (PMID 40733296, 2025). "SNPs in LTB are significantly correlated to oral cavity cancer in addition to TNF." (PMID 34539639, 2021).
oral submucous fibrosis (7 papers, 2015 to 2025). "Increased levels of TNF-α were observed in saliva of patients with oral submucous fibrosis (OSMF) and OSCC." (PMID 39911325, 2025).
ovarian endometriosis (7 papers, 2020 to 2025). A non-neoplastic disorder characterized by the growth of endometrial tissue in the ovaries. "In a previous study, miR-191-5p inhibited TNF-α-induced apoptosis of ovarian endometriosis and endometrioid carcinoma by targeting DAPK1." (PMID 40064799, 2025). "However, a comprehensive assessment of plasma, peritoneal fluid, and endometrioma TNF-α, IL-6, and IL-8 concentrations in women with ovarian endometriosis has not yet been performed." (PMID 40507929, 2025).
pleurisy (7 papers, 2012 to 2021). Inflammation of the pleura. "Another study documented that methanolic extract Sideritis bilgeriana suppressed TNF-α, IL-1β and leukocyte migration in carrageenan-induced pleurisy model, which is due to the presence of f phenolic and flavonoids content." (PMID 34684831, 2021). "Our study analyzes the role of TNF and TNF receptors in the control of the inflammatory process associated with Bacillus Calmette-Guérin (BCG)-induced pleurisy." (PMID 29973541, 2018). "We have previously reported that a mouse model of pleural infection shows that TNF or its receptors are crucial to control M. bovis BCG-induced pleurisy." (PMID 28890718, 2017). "In the CG-induced pleurisy, (−)-α-bisabolol exhibited a significant anti-inflammatory activity and this result could be possibly related to the significant decrease in the level of TNF-α in pleural inflammatory exudate." (PMID 29232831, 2017).
pouchitis (7 papers, 2020 to 2025). Acute inflammation in the intestinal mucosa of the continent ileal reservoir (or pouch) in patients who have undergone ileostomy and restorative proctocolectomy (proctocolectomy, restorative). "A cytokine storm (IL-1beta, IL-6, IL-8 and TNF-alpha), with the gain of function mutations in IL1β and the disruption of intestinal barrier, complete the picture of mucosal inflammation in pouchitis." (PMID 39770958, 2024). "More recently, the administration of exogenous lysozyme to rats with pouchitis has shown pouchitis amelioration associated with decreased TNF-α and IL-6 in the pouch tissue." (PMID 39770958, 2024). "Several studies have identified various factors linked to the development of pouchitis, such as extraintestinal manifestations, pancolitis, a history of PSC, and prior treatment with anti-tumor necrosis factor before colectomy." (PMID 39759750, 2024). "A systematic review and meta-analysis on use of anti-tumor necrosis factor therapy in pouchitis (n = 313) revealed rates of short-term and long-term clinical remission of 50% and 52%, respectively." (PMID 39130120, 2023). "Supplementation with exogenous lysozyme significantly ameliorated pouchitis, lowering the levels of inflammatory cytokines such as TNF-α and IL-6 in the pouch tissue." (PMID 38137976, 2023). "Tofacitinib, a pan-JAK inhibitor, has been used to successfully treat moderate to severe, anti-TNF resistant UC, although the evidence for its use in pouchitis and CD of the pouch is minimal." (PMID 36844648, 2022). "Its use has been shown to decrease inflammatory markers, including TNF-α, IFN-γ, and MMP-2/9, in patients with pouchitis." (PMID 40824057, 2025). "One case study describes a 20-year-old woman with pouchitis following IPAA surgery, who was refractory to antibiotics, steroids, anti-TNF, and vedolizumab." (PMID 36844648, 2022). "Cox regression analyses using the IPTW method, excluding the history of anti-TNF therapy as an adjusting background factor, also identified NLR as a prognostic factor for the development of pouchitis (adjusted HR, 3.67; 95% CI, 1.38–9.79; P = 0.01)." (PMID 33104762, 2020).
pregnancy (7 papers, 2012 to 2024). The status during which female mammals carry their developing young (EMBRYOS or FETUSES) in utero before birth, beginning from FERTILIZATION to BIRTH. "We found significantly increased expressions of BAFF mRNA or protein in whole tissue samples, and serum levels of BAFF, TNF-α and IL-6 in whole blood samples from patients with salpingitis and tubal pregnancy, in comparison to the control group." (PMID 31088412, 2019).
Pulmonary hemorrhage (7 papers, 2004 to 2025). Pulmonary hemorrhage is a bleeding within the lungs. "Co-injection of recombinant Rv0888NS/MS with an MPO inhibitor remarkably decreased recombinant Rv0888NS/MS-induced pulmonary hemorrhage, infiltration of inflammatory cells, and release of inflammatory cytokines (IL-6, TNF-α and IL-1β)." (PMID 29670633, 2018). "It has already been reported that the toxicity of TNF in phase I or II clinical trials are mainly chill, fever, local redness, swelling and pain, hypotension, nausea, vomiting, myalgia, fatigue and diarrhea, while pulmonary hemorrhage and severe hepatic dysfunction also have been observed." (PMID 15485573, 2004).
Right ventricular hypertrophy (7 papers, 2017 to 2025). In this case the right ventricle is more muscular than normal, causing a characteristic boot-shaped (coeur-en-sabot) appearance as seen on anterior- posterior chest x-rays. "Right ventricular hypertrophy was elevated to similar extents in both genotypes, probably due to the high levels of TNFα expression in this model." (PMID 28084316, 2017). "✓Isorhamnetin improved hemodynamic parameters (mPAP, RVSP) and alleviated right ventricular hypertrophy (RVHI, CSA).✓Inhibited TNF-α-induced HPASMC proliferation and inflammation.✓Upregulated BMP signaling." (PMID 40806510, 2025).
Rotavirus infection (7 papers, 2016 to 2023). Infection with any of the rotaviruses. "The scarcity of circulating rotavirus VP6-specific CD4+ T cells producing IFN-γ and TNF-α in rotavirus-vaccinated children following rotavirus infection was unexpected." (PMID 37268634, 2023). "Our findings demonstrate limited induction of anti-viral IFN-γ and/or TNF-α-producing CD4+ T cells in rotavirus-vaccinated Malawian children following the development of laboratory-confirmed rotavirus infection." (PMID 37268634, 2023). "In accordance, gene silencing of TNFR1 in these cells counteracted TNFα-mediated anti-Rotavirus effect, suggesting beneficial functions of TNFα signalling during Rotavirus infection." (PMID 30995806, 2019). "Rotavirus infection triggers the production of IL-8, IL-6, and TNF-α in IECs by activating the TLR3 and RIG-I pathways." (PMID 32038538, 2019). "However, circulating cytokine-producing (IFN-γ and/or TNF-α) rotavirus-specific VP6-specific CD4+ T cells were rarely detectable in children with rotavirus infection at both acute and convalescent stages." (PMID 37268634, 2023). "In response to rotavirus infection, the RAW264.7 mouse macrophage cell line produces type I IFN, IFN-γ, TNF-α, and inflammatory chemokines." (PMID 34946051, 2021). "PPARγ activation has been shown to block TNF-α production, while NAC suppresses TNF-induced NF-κB activation and inhibits rotavirus infection." (PMID 27382365, 2016). "Together, these findings indicate that the effector memory CD4+ T cells induced by rotavirus infection are unlikely to represent TNF-α or IFN-γ-producing VP6-specific CD4+ T cells." (PMID 37268634, 2023). "It is also important to note that TNF, a multi-functional proinflammatory cytokine, was repressed by both rotavirus and coronavirus, but IRF1, which is required to activate type I IFN responses, was activated following rotavirus infection." (PMID 31838832, 2020). "However, the rotavirus infection-induced effector memory CD4+ T cells were not targeted at the highly immunogenic rotavirus VP6 protein, and they did not produce TNF-α or IFN-γ." (PMID 37268634, 2023).
RSV bronchiolitis (7 papers, 2017 to 2025). "Clinical studies analyzing cytokine mediators in the bronchoalveolar lavage fluid (BALF) of patients with RSV bronchiolitis have implicated pro-inflammatory cytokines, including tumor necrosis factor (TNF)-α, as a major contributor to disease." (PMID 33080861, 2020). "In a previous longitudinal study within the same cohort as in the current study, we found that baseline TNFα and CCL5 gene expressions were associated with the clinical course of RSV bronchiolitis, as evaluated with the WDS and BROSJDD scores." (PMID 39403383, 2024). "In summary, we have demonstrated lower TNF‐α production by in vitro stimulated CD4+ T cells during severe RSV bronchiolitis in children who subsequently developed recurrent wheezing in the first 3 years of life." (PMID 31901157, 2020). "We demonstrated lower TNF‐α production by in vitro stimulated CD4+ T cells during severe RSV bronchiolitis in children that subsequently developed recurrent wheezing, compared with children with no subsequent wheeze." (PMID 31901157, 2020). "IL-6 and TNF-α mRNA and protein levels in bronchoalveolar lavage fluid in term infants with RSV bronchiolitis were greater than the control group." (PMID 29246125, 2017). "Moreover, TNF is a principal mediator of RSV-induced disease, and elevated nasal TNF levels correlate with severity in infants with RSV bronchiolitis." (PMID 41346628, 2025). "However, in preterm infants with RSV bronchiolitis, IL-6 and TNF-α proteins significantly decreased." (PMID 29246125, 2017).
Streptococcus pneumonia (7 papers, 2018 to 2023). "HMPV strongly suppresses IL-1β transcription in response to LPS or heat-killed Pseudomonas aeruginosa and Streptococcus pneumonia, while enhancing mRNA levels of IL-6, TNF-α and IFN-β." (PMID 37435074, 2023). "In patients, TNF-α levels increased in the presence of Acinetobacter baumanni, Corynebacterum striatum, Streptococcus pneumonia and Serratia marcescens when compared to infectious agents." (PMID 28840846, 2018). "The RYNM exhibited its therapeutic effects on Streptococcus pneumonia mainly via the regulation of cell proliferation and survival through the IL-6/IL-10/IL-17, Bax/Bcl-2, COX-1/COX-2, NF-κB and TNF-α signalling pathways." (PMID 33678123, 2021).